IL10 (interleukin 10)
Diseases named in the same sentence as IL10 in open-access papers (continued):
Sharing a sentence is not in itself a finding about the gene and the disease.
tumor (continued). "Among which, the expressions of anti-tumor cytokines including IL-2, IL-15 IL-17A, IFN-γ and TNF-α were up-regulated, while tumor-promoting cytokines including IL-4 and IL-10 were down-regulated in HER2.28ζ/PD-L1.BB CAR-T cells." (PMID 36402752, 2022). "In the tumor microenvironment, IL-10 functions to thwart immune responses and promote the immune escape of tumor cells." (PMID 35178106, 2022). "When we examined the tumor-killing ability of spleen lymphocytes in vitro, the upregulation of IL-10 in both nanovaccine and nanovaccine + aPD-1group with increased cytolytic effect on tumor cells." (PMID 35418151, 2022). "M2 macrophage polarization has been linked to the production of IL-4, IL-10, TGF-beta and Granulocyte Colony Stimulating Factor (G-CSF) by tumour cells." (PMID 36531051, 2022). "It was suggested that IL-10 produced by tumor cells inhibits macrophage-derived angiogenic molecules." (PMID 35626056, 2022). "IL-10 expression in the tumor, which is mainly produced by macrophages, reduces the expression of MHC-II and CD40 in DCs, affecting their capacity to mature and to present antigens and this is epigenetically regulated by DNMTs and HDACs." (PMID 35267487, 2022). "These investigations demonstrate that IL-10 stimulates an anti-tumor cytotoxic reaction and therefore a tumor regression leading to the prevention of metastases formation." (PMID 34152493, 2022). "The levels of IL-10, IL-4, and tumor markers in the observation group were significantly lower than those in the blank group (P < 0.05)." (PMID 36193493, 2022). "Some studies observed that the percentages of M2-macrophages are high in BC patients, especially a higher percentage of M2c subtype was observed in patients with advanced disease, highlighting the role of IL-10 in facilitating tumor progression." (PMID 36003772, 2022). "Cytokine screening indicated that IL-10 is significantly downregulated in Δ/Δ Pdgfrb primary tumor cell lines providing an explanation for the observed density-dependent proliferation defect." (PMID 36045346, 2022). "IL-10 also suppresses tumor-infiltrating DC maturation and their production of IL-12 to stimulate Th1 cells." (PMID 35493517, 2022). "In support of our results, AS101 sensitizes tumors to chemotherapy by blocking the tumor IL-10 autocrine loop which supports our findings." (PMID 35127342, 2022). "On the contrary, type II macrophages (or M2) promote tumor progression and are characterized by the secretion of factors with immune-suppressive activity such as TGFβ, IL-10, Arg, and IDO, which particularly affect cytotoxic CD8+ T cell functions." (PMID 36338519, 2022). "On the contrary, the M2-like macrophages are activated by the type 2 T helper cell (Th2) cytokines such as IL-4, IL-10 and IL-13, and exhibit promoting tumor capacity." (PMID 36518756, 2022). "In vitro experiments have shown that IL-10 has the capability to impair proliferation and cytotoxic activity of anti-tumor T-cells, thereby stimulating tumor growth." (PMID 35204426, 2022). "B cells can suppress anti-tumor T cells by secreting IL-10 and promote tumorigenesis by secreting antibodies exacerbating chronic inflammation." (PMID 36569871, 2022). "Multiplex cytokine analysis of conditioned media from cultures confirmed that IL-10 production was increased in WT mice as compared to cultures using tumor tissues from GCSFR−/− mice." (PMID 36033452, 2022). "Regulatory B (Breg) cells accumulate in the tumor environment, and it can produce high levels of IL-10." (PMID 36299502, 2022). "This is followed by interleukin-10 (IL-10) production in tumor mass with consequent tumor progression by inhibiting effector T-cell function in the TME." (PMID 36518249, 2022). "Interleukin-10 on the other hand, was previously thought to be largely immunosuppressive and supportive of tumor growth." (PMID 36138417, 2022).
tumor (continued). "Macrophages are a heterogenous population of terminally differentiated monocytes that range in their function from pro-inflammatory and anti-tumor (M1 phenotype) to pro-tumor tissue remodeling (M2 phenotype), induced by IL-4, IL-10, IL-13, and CSF-1." (PMID 36223740, 2022). "Fragile Treg is thought to have anti-tumor activity owing to its decreased expression of immunosuppressive factors such as interleukin 10 (IL-10) and its ability to secrete interferon-γ (IFN-γ)." (PMID 36359834, 2022). "IL-4 and IL-10 can suppress CD8+ tumor-infiltrating T cell function by recruiting immunosuppressive components, such as Tregs, M2 TAMs, and MDSCs." (PMID 36238278, 2022). "In contrast, IL-12, which we showed was increased by MK2 inhibition, is characterized as a major contributor of enhanced cytotoxic function in anti-tumor immunity, while IL-10 promotes tumor progression." (PMID 36362348, 2022). "Meanwhile, M2-polarized macrophages promote tumor progression, such as epithelial-mesenchymal transition, through IL-10 signaling pathway." (PMID 35669852, 2022). "We subsequently analyzed the influence of the anatomical tumor localization on concentrations of CgA, the NETest, as well as IL-1β, IL-6, IL-8, IL-10, IL-18, and TNF." (PMID 36294509, 2022). "The blockage promoted by IL-10 increases cytotoxic T cell function in the peritoneal cavity and limits tumor spread." (PMID 36142615, 2022). "They stimulate Treg differentiation and secrete several factors (e.g. TGFβ, TNFα, and IL-10) to create a favorable environment for tumor progression and to inhibit the anti-tumor effects of immune cells." (PMID 35805132, 2022). "IL-10 derived from Treg cells can act along with IL-35 to promote the exhaustion of CD8+ tumor-infiltrating lymphocytes (TILs), thus reducing anti-tumor immunity." (PMID 36119033, 2022). "IL-10 itself has an effective anti-tumor effect and also inhibits metastasis through immune-dependent mechanisms, including inhibition of infiltrating macrophages and angiogenic factors and activation of CD8+ T cell CTL." (PMID 36212143, 2022). "PD-L1/PD-1 blockade can restore the anti-tumor immunity by reactivating CD8+ T cells since Breg cells suppress CD8+ T cells by producing anti-inflammatory cytokine IL-10." (PMID 36033455, 2022). "In our study, we found that a high level of IL-10 was correlated with activated inflammatory environment in both tumor and normal samples." (PMID 35222434, 2022). "CS inhibited tumor growth, also resulted in a decrease in interleukin-4 (IL-4) and IL-10 (IL-10) and an increase in interferon production." (PMID 35774546, 2022). "Gefitinib, an EGFR inhibitor diminished the activation of these protein induced by IL-10, and inhibited tumor cells migration." (PMID 36038549, 2022). "Tumor derived stimuli (anti-inflammatory cytokines IL-4, IL-10, IL-13 and TGF-B), contribute to polarizing TAMs toward an immunosuppressive function as observed in peripheral blood." (PMID 36003772, 2022). "These suppressive myeloid cells expressed high levels of MARCO activated by tumor derived IL-10 that was induced via the transcription factor STAT3." (PMID 36310582, 2022). "While in our cohort, CD79B was correlated with higher IL-10 level in the vitreous (P=0.030, 1-β=0.740), which indicated higher tumor load in the vitreous cavity." (PMID 35928872, 2022). "Similar to IL-10, IL-8 secreted from TAMs plays a critical role in promoting tumor immunosuppression." (PMID 35955737, 2022). "Initially, in the control and in the early stages of the tumor, the IL-1β levels show a significant scatter among individuals, whereas those of TNFα and IL-10 have a narrower spread." (PMID 35053477, 2022). "M-CSF can recruit monocytes to the tumor tissue where IL-4, IL-10, IL-13 and other factors present in the tumor microenvironment can induce the differentiation of monocytes into TAMs." (PMID 35741108, 2022).
tumor (continued). "The tumor cells in the lesional skin of the tumor-stage shift to a Th2 phenotype, which is characterized by the production of IL-4, IL-5, IL-10, and IL-13." (PMID 36295105, 2022). "Their products, such as transforming growth factor-beta (TGF-β) and IL-10, tend to be tumor-promoting." (PMID 36077755, 2022). "Recently, a new subset of ILCs, regulatory ILCs, has been reported, which releases IL-10 following TGF-β signaling to play a tumor-promoting role." (PMID 36246629, 2022). "We also considered to examine the expression of IL-10, as this protein is pivotal for Treg-mediated immune tolerance and for promoting tumor growth; we measured the frequency of IL-10 producing Tregs by flow cytometry." (PMID 35860556, 2022). "While in the chemical carcinogenesis of skin, TNF-α is a promoter for tumor growth, IL-10 produced by B cells facilitates tumor growth in a TNF-α-dependent manner." (PMID 36033455, 2022). "IL-10 was previously identified in higher concentrations in HNSCCs in various studies, and a direct correlation between overall values and tumor stage was also reported." (PMID 36143043, 2022). "Tregs, DCs and tumor cells can produce and release the anti-inflammatory cytokine interleukin 10 (IL-10), which can promote the expression of HLA-G." (PMID 35185904, 2022). "Reduced levels of arginase 1, TGF-β and IL-10 in the tumor also provided evidence for reversion of the immunosuppressive conditions by VSV-S infection." (PMID 35197076, 2022). "In BC, IL-10 expression positively correlates with locally advanced disease and higher tumor grade and has been proposed as a good prognostic indicator of disease-free survival (DFS)." (PMID 35681689, 2022). "Glutamine deprivation in the TME, induced by glutamine-addicted tumor cells, promotes IL-23 expression on Tumor-Associated Macrophages (TAMs) through HIF-1α activation, which is related to higher IL-10 and TGF-β production and recruitment of Tregs." (PMID 36713558, 2022). "TMAs facilitate the ICs expression on tumor cells or produce IL-10, TGF-β, Arg-1, and IDO to impede T cell function." (PMID 36246629, 2022). "Th1 cells produce tumor necrosis factor alpha (TNF-α), interferon gamma (IFN-γ), interleukin (IL)-2 and IL-12 to mediate antitumor effects, while Th2 cells produce IL-4 and IL-10 which favor tumor growth." (PMID 35805995, 2022). "We found that all immune cells presented significant difference in infiltration between the high IL-10 group and low IL-10 group in tumor samples, and most of these cells were also significantly enriched in high IL-10 with normal tissues." (PMID 35222434, 2022). "Several paracrine factors, such as VEGF growth factor, IL6, and IL10 cytokines, are produced in cells undergoing lytic replication to modulate the tumor microenvironment to support the growth of the tumor cells." (PMID 36560704, 2022). "MDSCs suppress anti-tumor immune responses through several mechanisms; for example, by producing NO and ROS, depletion of cysteine or release of IL10 and TGFβ." (PMID 35681583, 2022). "For example, tumor-associated macrophages (TAMs) can generate immunosuppressive cytokines including TGF-B and IL-10 for example, which can drive preferential tumor outgrowth and contribute to poor patient outcomes." (PMID 36277972, 2022). "Increased tumor-derived IL-10 also correlated with higher MARCO expression in TCMs, and this was reversed by neutralizing antibodies to IL-10." (PMID 36310582, 2022). "PMCs prevent initial tumor cell invasion by secreting TNFα, CRC cells secrete IL‐6, and IL‐10 converts these anti‐tumorigenic PMCs to a pro‐tumorigenic M2 phenotype favoring tumor progression." (PMID 35791509, 2022). "The pro-tumorigenic role of GCSFR in inhibiting CD4 and CD8 T-cell responses by promoting IL-10 is recognized to play an important role in shaping the tumor microenvironment." (PMID 36033452, 2022).
tumor (continued). "MDSCs represent a heterogeneous population of immature myeloid cells that are accumulated during tumor progression and exhibit remarkable immunosuppressive and tumorigenic activities by secreting immunosuppressive cytokines such as IL-10 and TGF-β." (PMID 35676688, 2022). "By its anti-inflammatory and immunosuppressive activities, IL-10 support tumor progression, limiting efficient anti-tumor response." (PMID 36338516, 2022). "IL-10 production by TAMs can blunt anti-tumor responses by inhibiting the functions of APCs and subsequently blocking T cell effector functions." (PMID 35493517, 2022). "MDSCs are also reported to secrete exosomes packed with tumor-promoting factors like TGFβ, IL-10, MMP, and micro-RNAs that are transported to tumor sites and induce immunosuppression." (PMID 35122833, 2022). "In vivo experiments, the tumour volume was significantly smaller after eliminating Tregs with anti‐IL‐10 or anti‐CD25, which confirmed the effect of Tregs on tumour progression." (PMID 35969010, 2022). "Significantly increased concentration of CXCL16, IL-27, IFN-γ, and IL-17 and decreased concentration of immunosuppressive TGF-β and IL-10 were measured in serum samples and tumor tissues of 4T1+d-MAPPS-treated mice." (PMID 35757015, 2022). "Tumour conditioned media (TCM) significantly reduces HLA-DR expression, increases IL-10 release from monocytes and causes them to become suppressive." (PMID 34727230, 2022). "We also report that presence of IgG4 + B cells correlates with tumor expression of IL-10 and trends with expression of IL-4 by tumors." (PMID 35255925, 2022). "Angiopoietin 2 (ANGPT2) negatively influences tumor immunity by stimulating Tie-2-expressing monocytes/macrophages to secrete IL-10, leading to the expansion of Treg cells and inhibiting effector T-cell activation." (PMID 36013403, 2022). "B cell-derived IL-10 is a strong immunosuppressive cytokine in various autoimmune diseases, it is also important in tumor growth." (PMID 36033455, 2022). "IL-10 promotes monocyte differentiation towards an M2 phenotype macrophage and reinforces tumor characteristics, including cell proliferation and metastasis, by exerting immunosuppressive effects." (PMID 35455650, 2022). "Tregs cells expressing LAG-3 can suppress tumor-specific T cells and produce high levels of the immunoregulatory cytokines interleukin (IL)-10 and transforming growth factor-beta (TGF-β)." (PMID 36225938, 2022). "In contrast, the M2 phenotype is generally supposed to participate in immunosuppression and tumor promotion, which is formed after being exposed to macrophage colony-stimulating factor 1 (CSF-1), interleukin 4 (IL-4), IL-10, and IL-13." (PMID 36013403, 2022). "Regarding the tumor depth invasion in the esophageal wall (T staging), concomitant overexpression of HLA-G1 with IL-10 (p = 0.048) and MMP-21 (p = 0.043) was observed in ESCC patients with T3 depth of invasion." (PMID 36437782, 2022). "Tumor cells and CAfs, in tumor stromal, produce several cytokines such as IL-6, IL-8, IL-10, monocyte chemoattractant protein 1 (MCP-1), and regulated on activation, normal T cell expressed and secreted (RANTES)." (PMID 35986321, 2022). "Although IL-10 is an immunosuppressive cytokine, several studies have found that IL-10 induces effective antitumour immune surveillance and controls tumour growth." (PMID 34731284, 2022). "The reduction in IL-5 (p < 0.05), IL-6 (p < 0.01), and IL-10 (p < 0.05) in the tumor and spleen of the IHS-treated ApcMin/+ mice was further confirmed through ELISAs." (PMID 36014805, 2022). "CAR-T20 cells increased the level of human IFN-γ and decreased the level of IL-10 in tumor-bearing mice, both of which are related to the tumor-killing effect of CAR-T20 cells." (PMID 36352168, 2022).
tumor (continued). "Of note, chemokine alteration happened with 2 in the serum and 10 in the tumor tissue, among them, only IL10 was consistently upregulated in both serum and tumor tissue, suggesting that damp-heat syndrome affected local and systemic differently." (PMID 35957897, 2022). "In this research, the expression levels of tumor-associated macrophages (TAMs)-related markers (CCL2, CD68 and IL10) were a positive correlated PKIA expression, indicating an ontogenetic role of PKIA in HCC." (PMID 36204642, 2022). "The negative regulation of IL-10 on immune response in the tumor microenvironment serves to promote the immune escape of tumor cells." (PMID 35178106, 2022). "In lung cancer, IL-10 was also reported to mediate the recruitment of anti-inflammatory M2 macrophages and Tregs to the tumor." (PMID 35159208, 2022). "Microglia are intrinsically antitumorigenic; however, exposure to tumor-generated factors, such as IL-10, induces an immunosuppressive phenotype." (PMID 36338705, 2022). "In inflammatory and neoplastic diseases, B cells play a regulatory role by secreting regulatory cytokines, such as IL-10, or by relying on the secretion of antibodies." (PMID 35878202, 2022). "IL-10 is an inflammatory cytokine that suppresses anti-tumor immune responses by inducing T cell anergy and inhibition of T cell proliferation." (PMID 35444660, 2022). "Interleukin-10 (IL-10) has been thought to promote tumor immune escape by diminishing anti-tumor immune response in the tumor microenvironment." (PMID 35646056, 2022). "Hypoxia-induced cancer factors including IL-10 and TGF-beta can cause tumor-associated macrophages to develop into M2 macrophages, which have immunosuppressive properties." (PMID 36589842, 2022). "The immunosuppressive effect of IL-10, the function of recruitment to Treg makes IL-10 seem to promote tumor growth, while the changes in IL-10 levels after electrical pulses vary from experiment to experiment and need to be further verified." (PMID 36081554, 2022). "NK cells secrete a wide variety of anti-tumor cytokines such as IL-10, IL-5, IL-13, GM-CSF, IFN-γ, TNF-α." (PMID 36253762, 2022). "Tumor-associated macrophages are a primary source of anti-inflammatory molecules such as TGF-β, ARG1, and IL-10, as well as pro-inflammatory molecules such as tumor necrosis factor-α (TNF-α), IL1-β and CXCL10." (PMID 36276147, 2022). "These include tissue factor, microparticles, plasminogen activator inhibitor-1, cancer procoagulant, mucin, tumour-derived platelet agonists and inflammatory cytokines such as IL-6, IL-8 and IL-10." (PMID 36552961, 2022). "On the one hand, pro-tumorigenic cytokines secreted by neutrophil granulocytes and thrombocytes, including vascular endothelial growth factor, tumor necrosis factor-α, and interleukin-10, have been suggested to contribute to tumor progression." (PMID 35098389, 2022). "Similar to Tregs, Bregs produce high levels of IL-10 and suppress the host immune response, thereby exerting a pro-tumor effect." (PMID 36300115, 2022). "Inhibition of the JAK/STAT pathway rescues T-cell functionality both in our model and in-vivo, providing further evidence of IL-10 release being an important driving force of tumor immune escape." (PMID 35177622, 2022). "It has been reported that lactic acid can stimulate the M2 polarization of macrophages in tumor tissues and induce their production of factors such as IL-10 and VEGF." (PMID 35362480, 2022). "Furthemore, IL-10, considered as kind of anti-inflammatory interleukin can also be produced by DCs, suppressing the killing ability of immunity to tumour." (PMID 35406451, 2022). "STAT3 appears to be necessary for regulatory B (Breg) cells, a B cell counterpart to Tregs that produces anti-inflammatory IL-10 and is pro-tumor." (PMID 35406557, 2022). "For example, The interaction between MDSCs and macrophages can reduce the production of IL-12 by macrophages and increase the production of IL-10 by MDSCs, which promotes tumor progression." (PMID 35154134, 2022).